TRIM66 (tripartite motif containing 66)
Diseases named in the same sentence as TRIM66 in open-access papers (continued):
Sharing a sentence is not in itself a finding about the gene and the disease.
cancer (15 papers, 2015 to 2024). A tumor composed of atypical neoplastic, often pleomorphic cells that invade other tissues. "TRIM24 and TRIM28 are generally positively associated, while TRIM33 and TRIM66 are mostly negatively associated with cancer stemness in solid tumors." (PMID 33810347, 2021). "This strongly supports our claim that TRIM28 is positively associated, while TRIM66 is negatively associated with cancer stemness." (PMID 33810347, 2021). "Although the role of TRIM66 in cancer progression is not well understood, some studies suggest it functions as an oncogene." (PMID 39160596, 2024). "Although little is known about the expression pattern and biological functions of TRIM66 in cancers, a number of studies have revealed that altered expression of other TRIM family members is associated with cancers and cancer-related diseases." (PMID 26247633, 2015). "Surprisingly, this finding contrasts with our previously reported work showing a negative association between TRIM66 expression and cancer stemness across most solid TCGA tumors." (PMID 36674511, 2023). "As one of the members, TRIM66 takes a part in the behavior of various cancers." (PMID 35912155, 2022). "To sum up, we concluded that by targeting MMP9, TRIM66 could exert a cancer-promoting role in the progression of NSCLC cells." (PMID 35912155, 2022). "As for TRIM66, its role in cancer progression still remains largely unknown, although a few studies suggest that TRIM66 acts as an oncogene." (PMID 33810347, 2021). "The last member of the TIF1 family, TRIM66, is the least well known, with only several papers demonstrating its engagement in tumorigenesis, and neither of these papers depicted the TRIM66–cancer stemness association." (PMID 33810347, 2021). "Here, we demonstrate a significant negative association between TRIM66 expression and cancer stemness across most solid TCGA tumors." (PMID 33810347, 2021). "TRIM66 has been previously reported to play an oncogenic role in a number of human cancers." (PMID 31981447, 2020). "Several investigations indicate the oncogenic roles of TRIM66 in a number of human cancers." (PMID 31981447, 2020). "However, in cancer progression, the mode of action of TRIM66 was not linked to its’ chromatin-associated functions." (PMID 36674511, 2023). "However, the expression and functional implication of TRIM66 in cancers has been poorly defined." (PMID 26247633, 2015). "Research also revealed that TRIM66, TRIM25 and TRIM32 are involved in TGF-β signaling pathways to promote cancer cell proliferation and invasion." (PMID 36261847, 2022). "Next, we knocked down TRIM66 expression to study its effect on the cellular phenotype of NSCLC and found that knocking down TRIM66 attenuated migration, invasion, and EMT process of cancer cells." (PMID 35912155, 2022). "TRIM66 is one of the crucial members of TRIM, which has a deep connection with the behavior of various malignant tumors." (PMID 35912155, 2022). "On the other hand, TRIM66-associated transcriptome profiles are substantially depleted of targets for the c-Myc transcription factor, which reflects a negative correlation between TRIM66 expression and cancer stemness as assessed with stemness scores/signatures." (PMID 33810347, 2021). "In particular, six candidates (TRIM10, TRIM15, TRIM26, TRIM39-RPP21, TRIM62, and TRIM66) are members of the large tripartite motif (TRIM) family that consists of ubiquitin ligases involved in both innate immunity and cancer progression." (PMID 30102725, 2018). "Other studies have shown that SLC2A3 was directly related to SOX9, TRIM66, and HMGA1, which could promote cancer cell proliferation, migration, and invasion." (PMID 36247875, 2022). "TRIM24, TRIM28, TRIM33, and TRIM66 form the transcriptional intermediary factor 1 (TIF1) family of chromatin-binding proteins that are involved in DNA damage response (DDR) and show significant involvement in different cancer types." (PMID 33923045, 2021).
cancer (continued). "Additionally, TRIM66, TRIM52 and TRIM14 also play an oncogenic role in CRC, since they are involved in cancer proliferation and metastasis through the regulation of STAT3 pathway expression." (PMID 33673719, 2021). "For cancer initiation and development, TRIMs may play a role through the JAK/STAT3 pathway: knockdown of TRIM66 reduced the activation of phosphorylation levels of JAK2 and STAT3 in CRC cells, and significantly inhibited cell proliferation, migration, and invasion of CRC cells." (PMID 36261847, 2022).
tumor (7 papers, 2015 to 2025). "The transcription profiles associated with TRIM66 expression were significantly depleted, with stem cell markers in 23 tumor types and the normalized enrichment score ranging from −7.01 (LUAD) to −3.07 (PRAD)." (PMID 33810347, 2021). "On the other hand, the TRIM66-associated transcriptome profiles were consequently depleted with stemness-related markers in almost all tested tumor types." (PMID 33810347, 2021). "Although both cells were able to form tumors, the tumor growth rate of mice injected with TRIM66-siRNA cells was significantly slower than that of mice injected with control cells." (PMID 26247633, 2015). "The transcriptome profiles associated with high TRIM66 expression are robustly depleted with stem cell markers, and this phenomenon is universal regardless of the tumor type." (PMID 36674511, 2023). "TRIM66 was up-regulated in 64 out of 101 (63.4%) tumor tissues compared with bone cysts." (PMID 26247633, 2015). "Therefore, the TRIM28 positive association and TRIM66 negative association with tumor stemness is a common phenomenon across solid tumors." (PMID 33810347, 2021). "We demonstrated that regardless of the tumor type, only high TRIM28 expression consequently corresponds to higher tumor stemness, while high TRIM66 expression is negatively associated with tumor stemness." (PMID 33810347, 2021).
TRIM66 also shares sentences with these, for which no sentence is quoted: lung carcinoma (2 papers); bone cysts (1); colorectal cancer (1); head and neck squamous cell carcinoma (1); major depressive disorder (1); pancreatic adenocarcinoma (1); primary open-angle glaucoma (1); schizophrenia (1).